APAF1 (apoptotic peptidase activating factor 1)
Diseases named in the same sentence as APAF1 in open-access papers (continued):
Sharing a sentence is not in itself a finding about the gene and the disease.
Alcohol (1 paper, 2024). "Alcohol toxicity induced cell death and increased APAF-1 expression in the EtOH group." (PMID 39063550, 2024).
alcohol addiction (1 paper, 2024). "The functional enrichment analysis was conducted to unravel the mechanisms by which zonisamide affects alcohol addiction, specifically in relation to APAF-1 and TNF-α." (PMID 39063550, 2024). "This study investigated the effects of zonisamide treatment on cerebellar tissues in an experimental alcohol addiction (AA) model and its potential mechanisms of action, particularly regarding apoptotic protease activating factor-1 (APAF-1) and tumor necrosis factor-alpha (TNF-α) expression." (PMID 39063550, 2024).
Anxiety (1 paper, 2024). Intense feelings of nervousness, tension, or panic often arise in response to interpersonal stresses. "For instance, studies have supported the involvement of the APAF-1 annotated Toll-like signaling pathway in neurotransmitter alteration, anxiety, and cognitive dysfunction in individuals with AA." (PMID 39063550, 2024).
Atrophy (1 paper, 2017). Any weakening or degeneration, especially through lack of use. "Firstly, by controlling the expression of MAFbx/atrogin-1 and MurF1 in the early phase of atrophy development as demonstrated by others and secondly by controlling the expression of APAF-1/Caspase 9 in the late phase of atrophy development as proposed in our study." (PMID 28493972, 2017). "Therefore, we propose that in addition to the role of miRNA-23a in the early stage of atrophy, the downregulation of miRNA-23a in the late development phase of this disease might also play a significant role by modulating the miRNA-23a/APAF-1/Caspase 9 axis of regulation." (PMID 28493972, 2017).
B cell lymphomas (1 paper, 2016). "Taken together, Apaf-1 mislocalization to lipid raft domains is a critical factor in apoptosis resistance in clinical B-cell lymphomas and strategies to disrupt these cholesterol-rich domains appear to restore death sensitivity." (PMID 27863378, 2016). "Primary cells derived from 30 B-cell lymphoma patients, 7 T-cell lymphoma patients and 5 benign tumors were used for the assessment of Apaf-1 expression and its localization." (PMID 27863378, 2016). "As Apaf-1 expression is critical for post-mitochondrial death execution, these data provide a novel mechanism of the refractory and aggressive nature of this sub-class of B cell lymphomas." (PMID 27863378, 2016). "Taken together, our results implicate Apaf-1 mislocalization as a potential diagnostic and prognostic marker for DLBCL, and provide a novel therapeutic strategy for circumventing the drug refractory nature of this sub-class of B cell lymphoma." (PMID 27863378, 2016). "Furthermore, we identified novel small molecules that restored chemosensitivity of B cell lymphomas by affecting the release of Apaf-1 to the cytosol through an increase in intracellular reactive oxygen species (ROS), thereby facilitating apoptosis execution." (PMID 27863378, 2016). "As expected, Apaf-1 was detected in the cytosolic fractions of non-B cell lymphomas and non-cancerous tissues; however, in B cell derived lymphomas the protein was detected in membrane raft sub-domains rather than the cytosol." (PMID 27863378, 2016). "Moreover, as EBV infection is a frequent finding in patients with B cell lymphoma, the possibility of viral proteins, such as LMP1, hijacking Apaf-1 to the lipid fractions cannot be completely ruled out." (PMID 27863378, 2016).
cardiac hypertrophy (1 paper, 2016). "In contrast to the upregulation of miR-19b in cardiac hypertrophy and cardiac development, miR-19b is downregulated in coronary artery disease, which is closely linked to the Apaf1/caspase-dependent pathway." (PMID 27213338, 2016).
chlamydial infection (1 paper, 2015). "Our results suggest that the ratio of Apaf-1 and caspase-9 influences host susceptibility to chlamydial infection." (PMID 26290316, 2015). "Caspase-9 is generally activated in apoptosomes that contain Apaf-1, but the C9-i used here, which is an antagonist of caspase-9 self-cleavage, inhibited chlamydial infection." (PMID 26290316, 2015). "That is, caspase-9 sequestration by chlamydial infection from the host apoptosis cascade results in apoptosis repression of host cells, and Apaf-1 may compete against chlamydial utilization of caspase-9." (PMID 26290316, 2015). "Based on the results shown here, two hypotheses are proposed regarding an epistatic effect of apaf-1 and caspase-9 on chlamydial infection." (PMID 26290316, 2015). "In this case, Apaf-1 may indirectly confine Chlamydia to supporting host cell proliferation; however we are proposing another direct response of Apaf-1 against chlamydial infection." (PMID 26290316, 2015). "Because Apaf-1 shares domains with intracellular innate immune receptor NOD1, it may play a key role in the strategy to regulate chlamydial infection." (PMID 26290316, 2015).
cholangiocarcinoma (1 paper, 2025). A carcinoma that arises from the intrahepatic biliary tree (intrahepatic cholangiocarcinoma) or from the junction, or adjacent to the junction, of the right and left hepatic ducts (hilar cholangiocarcinoma). "Hsa_circ_0037104 in human umbilical cord‐derived MSCs‐derived exosomes could inhibit the proliferation and metastasis of cholangiocarcinoma cells by regulating the miR‐620/APAF1 axis." (PMID 39901896, 2025).
cholestasis (1 paper, 2025). Impairment of the bile flow caused by obstruction within the liver, or outside the liver in the bile duct system. "Moreover, Schisandrol B reduces atypical cell death induced by Apoptotic protease-activating factor 1 (Apaf-1) inflammasomes through the PXR/Forkhead box protein O1 (FoxO1)/Apaf-1 axis, thereby mitigating cholestasis-induced liver damage." (PMID 40832608, 2025).
co-infection (1 paper, 2002). "The percentage of cells with fragmented DNA induced by co-infection of Adv-Bax, Adv-APAF1 and Adv-Casp9 in U251 cells was only 0.6% (lower second left panel)." (PMID 11870542, 2002).
colorectal tumor (1 paper, 2016). "The knockdown of miR-23a in colorectal tumor cells was also able to allow the occurrence of 5-FU-induced apoptosis in vitro through the apoptotic protease activating factor 1 (APAF-1)/caspase-9 apoptotic pathway, consequently overcoming the initial resistance to this chemotherapeutic regiment." (PMID 27187371, 2016).
Encephalocele (1 paper, 2019). A neural tube defect characterized by sac-like protrusions of the brain and the membranes that cover it through openings in the skull. "To date, only two convincing mice with genetically determined encephalocele have been described: the tuft mouse, which involves a mutation of the Tet1 gene, and the fog mutant in which the Apaf1 gene is mutated." (PMID 31628096, 2019).
endometrial cancer (1 paper, 2021). Primary or metastatic malignant neoplasm involving the endometrium (mucous membrane that lines the endometrial cavity). "Our study showed a significant increase in APAF-1 levels after MIS/AMH treatment, indicating that MIS/AMH induces apoptosis in endometrial cancer cells." (PMID 34539902, 2021).
gastrointestinal stromal tumor (1 paper, 2017). "Also, it has been reported that HSP90β and Apaf-1 have a high binding affinity in AML cells and gastrointestinal stromal tumor (GIST) cells, which are c-KIT-positive cells." (PMID 29127384, 2017).
hairy cell leukaemia (1 paper, 2019).
hemangioma (1 paper, 2025). A benign vascular lesion characterized by the formation of capillary-sized or cavernous vascular channels. "In summary, circRNF111 binds to miR-27b-3p as a ceRNA and competitively inhibits miRNA binding to Apaf-1 mRNA, thereby increasing Apaf-1 protein expression and promoting the apoptosis of hemangioma endothelial cells." (PMID 40426921, 2025). "This study reveals that propranolol treats hemangiomas by activating the APAF1-mediated apoptotic pathway, while circRNF 111 induces propranolol-induced HUVEC apoptosis via miR-27b-3p/Apaf-1." (PMID 40426921, 2025).
Infantile Hemangioma (1 paper, 2025). "MiR-27b-3p can promote the apoptosis of hypoxic neurons by inhibiting Apaf-1, and this inhibition gradually decreases with age, similar to some infantile hemangiomas that gradually fade with age." (PMID 40426921, 2025).
insulinoma (1 paper, 2017). "Core components of the apoptotic machinery, including the effector caspase 3 and the apoptosome scaffolding protein Apaf-1, were also reduced in rat islets compared to insulinoma cells." (PMID 28212395, 2017).
liver cancer (1 paper, 2017). An epithelial or non-epithelial malignant neoplasm that arises from the liver. "Akt-knockout liver cancer cells showed lower p-Bad expression and higher Bad expression, which reduces Bcl-xL expression and promotes down-stream signals, such as cytochrome c, Apaf-1, caspase-9 and caspase-3 expression, and it subsequently contributes to apoptosis in cancer cells." (PMID 29502513, 2017).
MELAS (1 paper, 2017). "Apart from many targets including PINK1, FOXO1, PPARγ and Apaf-1 investigated before, MKNK2, GREM1 and EEF1A1 that might be potential targets of miR-27b-3p were revealed in the regulatory network of MELAS pathogenesis." (PMID 28139706, 2017).
metastatic tumors (1 paper, 2019). "We found that APAF1 protein was expressed in the primary tumor, but was only minimally expressed in the mutant metastatic tumor." (PMID 31321477, 2019). "Interestingly, APAF1 immunoreactivity was detected in the primary tumor but was reduced in the metastatic tumor." (PMID 31321477, 2019).
muscular atrophy (1 paper, 2017). The loss of muscle tissue due to inactivity or disease. "We established, in real time, the kinetic of miRNA-23a expression during development of this disease and examined the potential implication of the miRNA 23a/APAF-1/Caspase 9 axis of regulation in the apoptosis of skeletal muscle undergoing muscular atrophy." (PMID 28493972, 2017).
nodular melanomas (1 paper, 2008). "Among primary nodular melanomas, increased tumor thickness was associated with stronger expression of hypoxia markers TNF-α (p = 0.028) and Apaf-1 (p = 0.05), whereas tumor ulceration was associated with stronger expression of hypoxia markers HIF-1α (p = 0.05) and CAIX (p = 0.03)." (PMID 19061491, 2008). "Also, Apaf-1 was stronger in metastatic lesions when compared with primary nodular melanomas (p = 0.002)." (PMID 19061491, 2008).
oral cancer (1 paper, 2015). "In addition, apoptotic protease activating factor-1 (Apaf-1) was upregulated significantly by berberine in the KB oral cancer cells." (PMID 25634589, 2015).
oral squamous cell carcinoma (1 paper, 2013). "The present study aimed to confirm the role of hyper-methylation of the Apaf-1 and DAPK gene promoter regions in oral squamous cell carcinoma (OSCC) and the effect of the demethylation drug, 5-aza-2′-deoxycytidine (DAC)." (PMID 23946818, 2013).
pancreatic ductal adenocarcinoma (1 paper, 2023). An infiltrating adenocarcinoma that arises from the epithelial cells of the pancreas. "In turn, the overexpression of the same microRNA was associated with the invasion of pancreatic ductal adenocarcinoma cells by the downregulation of APAF-1 (apoptotic protease activating factor 1)." (PMID 37373398, 2023).
pancreatitis (1 paper, 2020). Inflammation of the pancreas. "In conclusion, by using suitable AP and CP models, we have defined the regulatory relationship between EMC6 and APAF1: EMC6 regulates acinar cell injury via APAF1 in pancreatic inflammatory diseases." (PMID 33177505, 2020). "The expression levels of EMC6 and APAF1 were markedly increased during pancreatitis progression and that APAF1 was positively regulated by EMC6." (PMID 33177505, 2020). "Our study also showed that following EMC6 inhibition in pancreatitis tissues, the expressions of ER stress markers and APAF1 were ameliorated." (PMID 33177505, 2020). "By proteome screening in PRSS1Tg mice pancreatitis tissues, we identified EMC6 and APAF1 as being closely associated with ER stress and apoptosis seen in pancreatic inflammatory diseases." (PMID 33177505, 2020). "Using these mice to screen for ER stress-associated and apoptosis-related proteins involved in pancreatitis development, we identified ER membrane protein complex subunit 6 (EMC6) and apoptotic peptidase activating factor 1 (APAF1) as potential regulatory proteins in pancreatic inflammatory disease." (PMID 33177505, 2020). "However, the exact mechanism by which EMC6 and/or APAF1 regulate the progression of pancreatitis is unclear and deserves further investigation." (PMID 33177505, 2020). "Our results further suggest that APAF1 is regulated by EMC6, induces apoptosis to injure acinar cells, and promotes inflammation in the development of pancreatitis." (PMID 33177505, 2020). "In the progression of pancreatitis, EMC6 was activated and then upregulated APAF1 to induce acinar cell apoptosis and inflammatory injury." (PMID 33177505, 2020).
periodontitis (1 paper, 2019). An acute or chronic inflammatory process that affects the tissues that surround and support the teeth. "In conclusion, P. gingivalis HmuY protein might contribute to the survival of PBMC in periodontitis by regulating the transcriptional profile of genes involved in apoptosis, such as FASL, caspase 9, APAF1, FAS, TNFSF10 (TRAIL), and BAK1." (PMID 31011284, 2019).
premature ovarian failure (1 paper, 2022). "From the aspect of apoptosis inhibitory genes, the mechanism of premature ovarian failure is also studied on the caspase family and the study on Apaf-1." (PMID 36388162, 2022).
rectal adenocarcinoma (1 paper, 2016). "Yet Garcia-Florez have made an opposite conclusion that high expression of APAF-1 lead to lower pCR in locally advanced rectal adenocarcinoma after neo-CRT." (PMID 27153549, 2016). "Therefore they have concluded that high level of pretreatment APAF-1 expression indicated higher rates of pCR that would be expected for paitents with locally advanced rectal adenocarcinoma when they were treated with neo-CRT." (PMID 27153549, 2016). "In this study, we are going to detect expression of COX-2 and APAF-1 genes in tissue samples obtained from pretreatment specimen for patients with locally advanced rectal adenocarcinoma and explore their potential value in predicting treatment response especially pCR to neo-CRT." (PMID 27153549, 2016). "Our research has shown that evaluation of APAF-1 and COX-2 expression on pretreatment specimen may be used to predict pathologic complete response to neo-CRT in patients with locally advanced rectal adenocarcinoma." (PMID 27153549, 2016). "In conclusion, the status of APAF-1 and COX-2 expression detected in pretreatment rectal tumor biopsies may be predictive in treatment response to neo-CRT for patients with locally advanced rectal adenocarcinoma." (PMID 27153549, 2016).
renal cell carcinoma (1 paper, 2006). "Renal cell carcinoma patients had median NIM levels of 51% in the younger group and 53% in the older group for APAF-1, the corresponding levels being 2 and 2%, respectively for DAPK-1." (PMID 17133271, 2006).
retinal diseases (1 paper, 2015). "In retinal diseases, studies showed that HDACis treatment upregulated the expression of Hsp70, downregulated the expression of apaf-1 and caspase 3, inhibited the translocation of cytochrome C and activation of Akt and Erk, increased the rate of cell survival, and decreased the apoptosis process." (PMID 26137316, 2015).
Sepsis (1 paper, 2011). Sepsis is defined as life-threatening organ dysfunction caused by a dysregulated host response to infection. "Therefore we used co-immunoprecipitation and immunoblotting to examine the effects of AdHSP on the sepsis-induced formation of complexes containing pro-caspase 3, caspase 8 and caspase 9, as well as Apaf-1." (PMID 22132083, 2011).
silicosis (1 paper, 2010). Silicosis is a respiratory disease caused by breathing in (inhaling) silica dust. "Measurement of the activity of caspases, Fas/FasL and Apaf-1 may open a new area for the early diagnosis of silicosis." (PMID 21120077, 2010).
skin aging (1 paper, 2021). The gradual irreversible changes in structure of skin that occur as a result of the passage of time.. "The TF E2F7 was also regulated by protein AIFM1 to downregulate target gene APAF1 in both young-adult and middle-aged skin aging." (PMID 34073305, 2021).
T cell lymphomas (1 paper, 2016). "Whereas, the total expression of Apaf-1 did not change, its sub-cellular localization was significantly different in DLBCL, compared to T cell lymphomas as well as cells derived from reactive lymphadenopathy biopsies." (PMID 27863378, 2016).
testicular cancer (1 paper, 2020). A primary or metastatic malignant neoplasm that affects the testis.
transitional cell carcinoma (1 paper, 2006). A malignant neoplasm arising from the transitional epithelium, usually affecting the urinary bladder, ureter, or renal pelvis. "Transitional cell carcinoma patients had median NIM levels of 58% in the younger group and 65% in the older group for APAF-1, the corresponding levels being 16 and 10%, respectively for DAPK-1 (P=0.4 and=0.8)." (PMID 17133271, 2006).
viral hepatitis (1 paper, 2025). An acute or chronic inflammation of the liver parenchyma caused by viruses. "Moreover, we found profound pathological alterations in the livers of Apaf-1+/− mice at 72 h post-infection, including dark color and significant virus-induced liver lesions or viral hepatitis." (PMID 39833169, 2025).